ASXL1 (ASXL transcriptional regulator 1)
Diseases named in the same sentence as ASXL1 in open-access papers (continued):
Sharing a sentence is not in itself a finding about the gene and the disease.
juvenile myelomonocytic leukemia (3 papers, 2012 to 2024). A myelodysplastic/myeloproliferative neoplasm of childhood that is characterized by proliferation principally of the granulocytic and monocytic lineages. "ASXL1 mutations are further detected in rare cases of juvenile myelomonocytic leukemia (JMML) and in RARS-T." (PMID 22436456, 2012).
refractory anemia (3 papers, 2012 to 2016). "In MDSs, ASXL1 mutations are more frequent in refractory anemia with excess of blasts (RAEB) than in the other forms such as refractory anemia with ring sideroblasts (RARS)." (PMID 22436456, 2012).
thymoma (3 papers, 2014 to 2024). A neoplasm arising from the epithelial cells of the thymus. "The extent of DNMT3A and ASXL1 mutations in thymoma should be explored, and treatments targeting epigenetic reprogramming should be considered in the future." (PMID 25000259, 2014). "In this article, we report the identification of DNMT3A and ASXL1 mutations in a cytogenetically normal stage IVB type B3 thymoma." (PMID 25000259, 2014). "In fact, the majority of previously observed ASXL1 mutations occur in the same exon as this mutation, exon 12.26, 27 Thus, both the type and location of this somatic mutation strongly suggests mutations in ASXL1 have a causal role in the etiology of thymomas." (PMID 25000259, 2014). "Our results show that mutations in DNMT3A and ASXL1 have a role in the development of thymoma." (PMID 25000259, 2014). "Genes involved in histone modification (BAP1, 13%; SETD2, 11%; ASXL1, 4%), chromatin remodelling (SMARCA4, 4%), and DNA methylation (DNMT3A, 7%; TET2, 4%; WT1, 4%) were frequently mutated in thymic carcinomas, but not thymomas." (PMID 35884448, 2022). "In a recent study, nine out of thirty nine mutated genes (23%) were involved in epigenetic regulation, with 34% of TCs exhibiting recurrent mutations in seven of them (BAP1, ASXL1, SETD2, SMARCA4, DNMT3A, TET2, and WT1), an observation which was not present for thymomas." (PMID 38338833, 2024).
type II diabetes (3 papers, 2024 to 2025). "For any CHIP, DNMT3A CHIP, TET2 CHIP, and ASXL1 CHIP, the top outcomes reflected CpG sites related to age/aging, alcohol consumption, smoking, and multiple CVD-related traits including body mass index (BMI), type II diabetes, and fasting insulin." (PMID 39070619, 2024).
age (2 papers, 2021 to 2023). A temporal measurement of the time period elapsed since an identifiable point in the life cycle of an organism. "Somatic mutations of ASXL1 are frequently detected in age-related clonal hematopoiesis (CH)." (PMID 33758188, 2021).
autoimmune disease (2 papers, 2022 to 2025). A disorder resulting from loss of function or tissue destruction of an organ or multiple organs, arising from humoral or cellular immune responses of the individual to their own tissue constituents. "Various molecular abnormalities like TET2, SRSF2, ASXL1, and RAS are reported in the pathogenesis of CMML, but no such mutations have been described to explain the strong association of autoimmune diseases and severe inflammatory phenotype seen in CMML." (PMID 35281324, 2022).
bladder cancer (2 papers, 2020 to 2021). "CircASXL1, located in chr20:30954186-30956926 and formed by exons 2 and 3 of ASXL1, has been revealed to have correlation with both tumor stage and lymph node invasion in bladder cancer." (PMID 34127015, 2021).
colon cancer (2 papers, 2010 to 2025). "Our genome-wide strategy to identify immunogenic NMD-resistant transcripts has identified five novel cMS mutations (SFRS12IP1, MED8, ASXL1, FBXL3, RGS12) in at least 45% of eleven MSI-High colon cancer cell lines tested." (PMID 21209843, 2010).
COVID-19 (2 papers, 2022 to 2023). A disease caused by infection with severe acute respiratory syndrome coronavirus 2. "Given that CHIP is driven by mutations in multiple epigenetic regulators, such as DNMT3A, TET2, and ASXL1, we hypothesized that altered chromatin activity might play a critical role in facilitating IFN-γ response gene expression in severe COVID-19." (PMID 36229591, 2022).
dysplasia (2 papers, 2021 to 2025). A usually neoplastic transformation of the cell, associated with altered architectural tissue patterns. "CHIP is currently defined by the presence of somatic mutations commonly seen in hematologic malignancies (e.g., DNMT3A, TET2, ASXL1) in individuals without cytopenia or dysplasia." (PMID 41464583, 2025).
glial neoplasms (2 papers, 2020 to 2023). "Although ASXL1 mutations are usually seen in non-glial neoplasms, rare mutations have been described in DMG/K27M." (PMID 32680567, 2020).
intracerebral hemorrhage (2 papers, 2025 to 2026). A cerebrovascular disorder characterized by bleeding into one or both cerebral hemispheres including the basal ganglia and the cerebral cortex. "While the presence of any CH mutation is associated with intracerebral hemorrhage (ICH) (OR = 1.21, P = 0.02), specific mutations, SRSF2 and ASXL1 are protective against ICH (OR = 0.9, P = 0.04) and nontraumatic subarachnoid hemorrhage (OR = 0.92, P = 0.03), respectively." (PMID 40093911, 2025).
Kabuki syndrome (2 papers, 2021 to 2025). Kabuki syndrome (KS) is a multiple congenital anomaly syndrome characterized by typical facial features, skeletal anomalies, mild to moderate intellectual disability and postnatal growth deficiency. "Similarly, there is a close resemblance between the DNAm signatures associated with pathogenic variants in ASXL2 and ASXL1 causing Shashi-Pena and Bohring-Optiz syndromes respectively, and between KDM6A and KMT2D variants causing Kabuki syndrome." (PMID 39843918, 2025).
thymic carcinoma (2 papers, 2022 to 2023). Thymic carcinoma (TC) is a type of thymic epithelial neoplasm characterized by a high malignant potential. "In thymic carcinomas, mutations were found in genes involved in the histone modification pathway, including BAP1 (6%), SETD2 (11%), ASXL1 (4%), and in chromatin remodeling genes, such as SMARCA4 (4%)." (PMID 38201593, 2023).
Trisomy 8 (2 papers, 2021 to 2024). "The elevated frequencies of both RAD21 gene promoter methylation and ASXL1 mutations in patients with trisomy 8 compared to other cytogenetic groups, along with the fact that RAD21 gene is located on chromosome 8, lay the groundwork for further research into this specific cytogenetic group." (PMID 39459611, 2024). "Trisomy 8 is frequently associated with mutations in driver genes including RUNX1, ASXL1, DNMT3A43, TET244, and IDH1 and IDH245." (PMID 34707142, 2021).
Alagille syndrome (1 paper, 2020). "Duplication of JAG1, BTBD3, and FLRT3, or ASXL1 induces Alagille syndrome, neurological dysfunction or chromatin remodeling." (PMID 32684981, 2020).
Arterial thrombosis (1 paper, 2024). The formation of a blood clot inside an artery. "In the whole cohort of patients, molecular classification identified PV/ET patients at higher risk of disease progression whereas DNMT3A/TET2/ASXL1 mutations were associated with higher risk of arterial thrombosis." (PMID 38263537, 2024).
blood disease (1 paper, 2017). A disease that occurs in the blood. "Since Asxl1 mutation alone did not produce obvious blood diseases in mice, we sought to determine if this mutation functions as a facilitator for leukemogenesis." (PMID 28697759, 2017). "There were no obvious blood diseases in mutant mice throughout their life-span, indicating Asxl1 mutation alone was not sufficient for leukemogenesis." (PMID 28697759, 2017).
cervical cancer (1 paper, 2024). A primary or metastatic malignant neoplasm involving the cervix. "Three mutational markers (TNFAIP3, BRCA1, ASXL1) of non-responders were found to be shared with the DNA markers from patients with progressive disease in an independent cervical cancer cohort (GEO repository: GSE205247)." (PMID 38951894, 2024).
cholangiocarcinoma (1 paper, 2023). A carcinoma that arises from the intrahepatic biliary tree (intrahepatic cholangiocarcinoma) or from the junction, or adjacent to the junction, of the right and left hepatic ducts (hilar cholangiocarcinoma). "Young‐onset cholangiocarcinoma does appear to have distinct genetic features, including increased frequency of mutations in ASXL1 and KMTC2, compared with typical‐onset cholangiocarcinoma." (PMID 37212509, 2023). "A recent analysis of patients aged 15 through 45 years with cholangiocarcinoma demonstrated that younger patients were more likely to carry additional sex combos like 1 (ASXL1) and lysine methyltransferase 2c (KMT2C) mutations compared with older patients with cholangiocarcinoma." (PMID 37212509, 2023).
chronic obstructive pulmonary disease (1 paper, 2023). A chronic and progressive lung disorder characterized by the loss of elasticity of the bronchial tree and the air sacs, destruction of the air sacs wall, thickening of the bronchial wall, and mucous accumulation in the bronchial tree. "Our findings are consistent with the notion that CH with TET2 mutations is different from CH with DNMT3A or ASXL1 mutations as indicated by some clinical studies, for example, CH with TET2 mutations has been linked to chronic obstructive pulmonary diseases but not CH with DNMT3A mutations." (PMID 37083525, 2023).
cutaneous squamous cell carcinoma (1 paper, 2024).
Cyanosis (1 paper, 2018). Bluish discoloration of the skin and mucosa due to poor circulation or inadequate oxygenation of arterial or capillary blood. "Here, we show that Asxl1 ablation in mice results in postnatal lethality due to cyanosis, a respiratory failure." (PMID 30389914, 2018).
diffuse midline glioma (1 paper, 2021). A diffuse glioma that arises from the midline structures of the central nervous system. "ASXL1 gene was mutated in diffuse midline glioma that originated within the pons." (PMID 34257334, 2021).
endothelial dysfunction (1 paper, 2025). In vascular diseases, endothelial dysfunction is a systemic pathological state of the endothelium (the inner lining of blood vessels) and can be broadly defined as an imbalance between vasodilating and vasoconstricting substances produced by (or acting on) the endothelium. "As was mentioned earlier in the article, direct evidence linking ASXL1 mutations to endothelial dysfunction is limited, but the pro-inflammatory environment induced by these mutations can adversely affect endothelial cells." (PMID 39997650, 2025). "The inflammatory milieu driven by ASXL1 mutations, marked by elevated cytokines like TNF-α, may indirectly contribute to endothelial dysfunction and increased cardiovascular risk." (PMID 39997650, 2025).
gastric cancer (1 paper, 2017). A primary or metastatic malignant neoplasm involving the stomach. "Most of the highest expressed circRNA genes in gastric cancer samples are also present in tumor-adjacent tissue (CFLAR, CORO1C, HIPK3, ASXL1 and SFMBT2)." (PMID 29109417, 2017).
Gorlin syndrome (1 paper, 2025). "Genes such as SUFU, which harboured an lpVUS in one of the patients diagnosed at 22 years of age, is known for its association with Gorlin syndrome, while ASXL1 and NOTCH2, identified in another patient, have been implicated in familial CRC." (PMID 40627234, 2025).
hypercoagulability (1 paper, 2025). "CHIP is characterized by the expansion of hematopoietic stem cell clones harboring somatic mutations in genes such as TET2, DNMT3A, and ASXL1, which are implicated in inflammation, atrial remodeling, and hypercoagulability." (PMID 40141381, 2025).
iron overload (1 paper, 2020). "The higher incidence of ASXL1 and TET2 gene mutations in our iron overload (IO) MDS patients suggests that IO may be involved in the pathogenesis of MDS." (PMID 33178287, 2020).
lung adenoma (1 paper, 2021). A benign, well circumscribed epithelial neoplasm that arises from the bronchus or the lung parenchyma. "Two SNVs in Asxl1 were identified in mouse lung adenomas induced by MNU in the background of a KrasG12D mutation." (PMID 33435458, 2021).
lymphoid neoplasm (1 paper, 2022). A neoplasm composed of a lymphocytic cell population which is usually malignant (clonal) by molecular genetic and/or immunophenotypic analysis. "A large cohort of 28 patients reported many mutations, which are implicated in other myeloid malignancies, e.g., TET2, MLL4, NF1, ALK, and ASXL1; many of these genes are driver mutations in different myeloid and lymphoid neoplasms." (PMID 36358690, 2022). "Some gene mutations frequently identified in myeloid or lymphoid neoplasms have also been observed in RDD, e.g., ASXL1, TET2, and DNMT3A." (PMID 36358690, 2022).
lymphoplasmacytic lymphoma (1 paper, 2023). A clonal neoplasm of small B-lymphocytes, lymphoplasmacytoid cells, and plasma cells involving the bone marrow, lymph nodes, and the spleen. "A frameshift variant, NM_015338.6:c.1934dup (rs750318549) in ASXL1, was observed in two cases, one with lymphoplasmacytic lymphoma at the age of 73 and one with CLL at the age of 50." (PMID 37379307, 2023).
migraine (1 paper, 2025). "Our analyses revealed 283 genes, including some newly associated with migraine: MAML3, CELF4, IRX1, ASXL1, SPOCD1, CXCL, and TLR4." (PMID 41420111, 2025).
myeloid sarcoma (1 paper, 2024). A tumor mass composed of myeloblasts or immature myeloid cells. "In another patient with myeloid sarcoma and history of treatment-related AML, this included an ASXL1 indel and FLT3 ITD." (PMID 39687881, 2024).
nutritional deficiency (1 paper, 2024). "Screening of CHIP-associated genes, particularly TET2, DNMT3A and ASXL1, can be an optional measure in CAR-T manufacturing in some elderly populations presenting CHIP bias, such as immune cytopenia, marrow dysplasia, and nutritional deficiency." (PMID 38191582, 2024).
osteonecrosis (1 paper, 2023). A none disease characterized by death of bone tissue due to a lack of blood supply. "Together, these data suggested that the four key differential genes ASXL1, BNIP3L, FCGR2A and TYROBP were significantly associated with osteonecrosis of the femoral head." (PMID 36631868, 2023). "The results showed that eighteen differential genes were annotated, among which BNIP3L, ASXL1, FCGR2A and TYROBP were highly correlated with osteonecrosis." (PMID 36631868, 2023). "Through animal experiments, it was confirmed that ASXL1, BNIP3L, FCGR2A and TYROBP screened from the comparative analysis of multiple genes in the database were closely related to GIONFH, which is important for early diagnosis of Glucocorticoid-induced osteonecrosis of the femoral head." (PMID 36631868, 2023). "By consulting the literature, we could not find that the BNIP3L and ASXL1 were directly related to the occurrence of osteonecrosis." (PMID 36631868, 2023).
pancreatic cancer (1 paper, 2018). "A variant in ASXL1 (p.R693X rs373221034) has been reported to be somatically mutated 38 times in haematopoietic/lymphoid tissue/28 times in pancreatic cancer (ID = COSM51388) in the COSMIC database." (PMID 29641532, 2018).
RASopathies (1 paper, 2024). "Similar to RASopathies, in which pathogenic variants in many genes lead to overlapping phenotypes that can be treated by inhibiting a common pathway, our data identifies common pathways for ASXL1 variants that can be targeted for both disease states." (PMID 39614348, 2024).
respiratory failure (1 paper, 2018). The significant impairment of gas exchange within the lungs resulting in hypoxia, hypercarbia, or both, to the extent that organ tissue perfusion is severely compromised. "The reduced surfactant production and excessive glycogen content associated with defective phospholipid synthesis caused by the absence of Asxl1 in Type II cells leads to respiratory failure and poor neonatal mortality." (PMID 30389914, 2018). "However, Asxl1−/− mice died within 1.5 h of birth due to respiratory failure." (PMID 30389914, 2018).
severe combined immunodeficiency (1 paper, 2015). Severe combined immunodeficiency (SCID) comprises a group of rare monogenic primary immunodeficiency disorders characterized by a lack of functional peripheral T lymphocytes resulting in early-onset severe respiratory infections and failure to thrive. "To determine the effects of ASXL1 correction in vivo, we xenografted uncorrected KBM5 cells and two homozygous ASXL1 mutation-corrected KBM5 clones into non-obese diabetic–severe combined immunodeficiency–IL-2Rγ null (NSG) mice." (PMID 26623729, 2015).
skin nodules (1 paper, 2024). "The patient with skin nodules and the pathology diagnosed BPDCN, the next generation sequencing of skin nodules showed mutations of IDH2 and ASXL1." (PMID 38527844, 2024).
small cell lung carcinoma (1 paper, 2024). Small cell lung cancer (SCLC) is a highly aggressive malignant neoplasm, accounting for 10-15% of lung cancer cases, characterized byrapid growth, and early metastasis. "Intriguingly, ASXL3, similar to ASXL1 and ASXL2, forms a PR-DUB complex with BAP1 but also exclusively interacts with BRD4, which binds to acetylated histones via its bromodomains in small cell lung carcinoma." (PMID 38791157, 2024). "In small cell lung cancer patients, BRD4 interacts with ASXL3 but not ASXL1 or ASXL2." (PMID 38791157, 2024).
thymic lymphomas (1 paper, 2021).
viral infection (1 paper, 2023). "Cells under inflammatory stress are expected to produce poor-quality results, especially under stressors such as viral infection and CHIP (typically caused by clones carrying mutations in epigenetic regulators like TET2, DNMT3A and ASXL1), contributing to a lower fraction of high-quality reads." (PMID 37372428, 2023).